SIRT1 (sirtuin 1)
Diseases named in the same sentence as SIRT1 in open-access papers (continued):
Sharing a sentence is not in itself a finding about the gene and the disease.
breast cancer (continued). "Compounds 4a–n have been evaluated in p300, PCAF, SIRT1/2, EZH2 and CARM1 enzyme assays, and in NB4 human acute promyelocytic leukemia (APL), U937 AML, MCF-7 breast cancer and SH-SY5Y neuroblastoma cells, to determine their effects in cell cycle phases and apoptosis (sub-G1 peaks) induction." (PMID 32650558, 2020). "Additionally, AMPK-triggered nuclear translocation of GAPDH leads to Sirt-1 release from the complex deleted in breast cancer-1 (DBC-1), an inhibitor of Sirt-1, thereby enhancing Sirt-1 transcriptional activity." (PMID 33049944, 2020). "In the breast carcinoma cell line MCF-7 though, the opposite effect was observed, Sirt1 inhibition by EX-527 led to cell cycle arrest while treatment with Sirtinol or Salermide (Sirt1/2 inhibitors with a stronger effect on Sirt2) resulted in cell death." (PMID 32426286, 2020). "However, some studies argue that SIRT1 suppresses cancer cell migration and invasion, such as, by targeting ARHGAP5 in gastric cancer, by inhibiting the TGF-β/Smad4/MMP-7 axis in breast cancer and by regulating autophagy in CRC." (PMID 31068761, 2019). "In this regard, SIRT1 knockdown or SIRT1 downregulated by a combined treatment (Resveratrol + Pterostilbene) produced decreased γH2AX and reduced DNMT1, DNMT3a, and DNMT3b in breast cancer cells." (PMID 31261609, 2019). "Elevated SIRT1 deacetylase modulate the nuclear localization of FOXO1, an apoptosis associated EMT-TF and deacetylate the acetylated DNMT1 thus inhibition of SIRT1 enhance the DNMT1-mediated silencing of ER-α and CDH1 reflecting mesenchymal acquisition in MDA-MB-231 breast cancer cells." (PMID 35582717, 2019). "Both are non-toxic and cheap treatments eliciting SIRT1 inhibition with the potential of significantly improving the management of breast cancer patients." (PMID 30739913, 2019). "While, SIRT1, 4, 5, and 7 have been reported to be upregulated in certain cancers, the same SIRT1as well as SIRT2 and SIRT6 is shown to be downregulated in breast cancer, hepatic cell carcinoma, gliomas, gastric carcinomas and colon adenocarcinoma." (PMID 32010617, 2019). "They found that SIRT1 upregulation suppresses cancer metastasis by reducing EMT, consequently maintaining E-cadherin expression; whereas SIRT1 repression promotes metastasis of breast epithelial cells in an orthotopic model of breast cancer." (PMID 30380732, 2018). "In this case, 50% (60 of 120) malignant tissues and 94% (30 of 32) metastases were nuclear SIRT1 negative/low, suggesting a reverse correlation between nuclear SIRT1 and breast cancer progression." (PMID 30038266, 2018). "SIRT1-mediated epigenetic silencing of survivin occurs through deacetylating the H3K9 marker on the survivin promoter, consequently suppressing its transcription in mammary tumors." (PMID 30380732, 2018). "It is also worth mentioning that our subgroup analyses of the correlations between abnormal Sirt1 expression and breast cancer or gastric cancer did not lead to the same conclusions as the meta-analysis." (PMID 29029516, 2017). "In breast cancer, a negative feedback loop exists between SIRT1 and miR-200a, an epithelial phenotype-defining miRNA." (PMID 27379175, 2016). "SIRT1 is overexpressed in various types of cancer including colon cancer, breast cancer, prostate cancer, squamous cell carcinoma, and human non-small cell lung cancer cell lines." (PMID 26988912, 2016). "However, it should be kept in mind that opposing evidence in breast cancer cells suggests that SIRT1 protects from EMT, and metastasis and SIRT1 downregulation is required for the progression to EMT and invasiveness." (PMID 27367735, 2016). "SIRT1 inhibition was reported to reduce both the nuclear FOXO1 levels and MRP2 expression while enhancing cytotoxic effects of paclitaxel and doxorubicin in tamoxifen-resistant breast cancer cells." (PMID 25569080, 2015).
breast cancer (continued). "SIRT1 knockdown reproduced the effects of combinatorial resveratrol and pterostilbene-induced SIRT1 down-regulation through inhibition of both telomerase activity and γ-H2AX expression in HCC1806 breast cancer cells." (PMID 26459286, 2015). "This conclusion is consistent with our previous work showing that development of skin tumors, intestinal tumors, and mammary tumors in mice is not influenced by SIRT1 catalytic activity." (PMID 25380034, 2014). "Immunohistochemistry was performed to examine the expression of SIRT1, N1IC, and Snail, and the combined expression of SIRT1 and N1IC, using tissue microarrays containing breast cancer tissue and matched adjacent normal breast tissue from 150 breast cancer patients." (PMID 25420528, 2014). "SIRT1 mRNA and protein levels were significantly lower in cell lines derived from mammary tumors lacking BRCA1 compared with cell lines derived from tumors without BRCA1 mutation." (PMID 25486244, 2014). "Ueno and colleagues demonstrated that FZD7 expression is important for cell survival in colorectal cancer; however the role that SIRT1 plays had not been explored in breast cancer cells." (PMID 24897117, 2014). "In our mice, regardless of Sirt1 genotype, mammary tumors all had similar levels of SIRT1 and ERα protein levels as assessed by immunohistochemistry, suggesting that absence of SIRT1 catalytic activity does not appear to affect ERα expression in this context." (PMID 24278473, 2013). "SIRT1-FL deacetylation activity is fine-tuned by several mechanisms, including interaction with the SIRT1-FL activator AROS (Active Regulator Of SIRT1–FL), and the SIRT1-FL-inhibitor DBC-1 (Deleted in Breast Cancer-1)." (PMID 20975832, 2010). "The predictions revealed that the mechanism of sinapic acid in breast cancer may be due to regulation of multiple proteins like CTNNB1, PRKCA, CASP8, SIRT1, and cytochrome enzymes (CYP1A1 & CYP3A4); the majorly regulated pathway was predicted to be ‘Pathways in cancer’." (PMID 38081857, 2023). "Moreover, SIRT1 forms a negative feedback loop with miR-200a, with overexpression of SIRT1 being related to decreased levels of miR-200a in patients suffering from breast cancer." (PMID 35087589, 2022). "SIRT1 overexpression has already been found in several tumor cells, including acute myeloid leukemia (AML) and primary colon, prostate, melanoma, and non-melanoma skin cancers, whereas SIRT1 low-expression was demonstrated in breast cancer and hepatic cell carcinomas." (PMID 35212616, 2022). "On the contrary, SIRT1 overexpression by resveratrol (a classical activator of sirtuins) was reported to increase the expression of CD36 (a transmembrane receptor that regulates apoptosis and angiogenesis) to cytotoxic levels, thus inhibiting the proliferation of MCF-7 breast cancer cells." (PMID 36291902, 2022). "This indicates that SIRT1 upregulated V-ATPase activities to increase lysosomal function, which halted the secretion of exosomes containing hydrolases that degrade the extracellular matrix, thereby ultimately inhibiting the aggressiveness of MDA-MB-231 breast cancer cells." (PMID 36291902, 2022). "SIRT1 has been demonstrated to modulate several intracellular signaling protein molecules, including protein kinase B (PKB), B-cell lymphoma 2 (Bcl-2), metadherin (MTDH), Frizzled 7, EMT-related proteins, and the cluster of differentiation 36 (CD36), in breast cancer cells." (PMID 36291902, 2022). "Recently, a study demonstrated that CRISPR-Cas9-mediated deletion of SIRT1 promotes the release of exosomes (containing unique cargoes and hydrolases that degrade the extracellular matrix), impairs lysosomal function, and inhibits lysosomal acidification in MDA-MB-231 breast cancer cells." (PMID 36291902, 2022).
breast cancer (continued). "Furthermore, following the downregulation of SIRT1, there is significantly increased secretion of cathepsin, which degrades ECM and allows tumor cells to invade the surrounding tissues, which ultimately promotes breast cancer metastasis." (PMID 34485600, 2021). "In breast cancer, IL-6 pre-treatment followed by SIRT1 activation by SRT1720 combined with dual PI3K/mTOR inhibitor NVP-BEZ235 obviously increased sensitivity of the cancer stem cells to radiation, so that late stage breast cancer cells therapeutic effect was effectively improved." (PMID 33790792, 2021). "However, SIRT1 demonstrated a potential positive trend with the expression levels of cytoplasmic FOXO3 in HER2+ breast cancer subtypes with negative estrogen receptor status (ER-)." (PMID 31357743, 2019). "SIRT1 upregulation has already been demonstrated in some cancer cells, such as acute myeloid leukemia (AML) and primary colon, prostate, melanoma, and non-melanoma skin cancers, while SIRT1 downregulation was described in breast cancer and hepatic cell carcinomas." (PMID 31261609, 2019). "However, SIRT1-dependent epigenetic regulation of H3 and H4 acetylated histone marks, and consequently cancer-related gene expression in human breast cancer, has not been investigated yet." (PMID 30093977, 2018). "In addition, the interaction between CHES1 and SIRT1 not only existed in ERα-positive breast cancer cells but in many ERα-negative cells." (PMID 29752474, 2018). "Furthermore, we revealed that SIRT1 deficiency is associated with substantial induction of acetylated markers on six breast cancer-related gene promoters: AR, BRCA1, ERS1, ERS2, EZH2, and EP300, suggesting an active role of SIRT1 in regulating the expression of these genes in BC." (PMID 30380732, 2018). "Thus, it is plausible to speculate that SIRT1 might regulate SMAD4 and breast cancer metastasis in a SIRT7 deacetylase-dependent manner." (PMID 28827661, 2017). "All the results together, the SIRT1 protein and Notch1 signaling mainly manifested in the level of N1IC played an important role in the prognosis of patients, and may represent therapeutic targets for breast cancer." (PMID 25420528, 2014). "In addition, we classified breast cancer patients into four groups according to the combined expression status of SIRT1 and N1IC as follows: SIRT1-high/N1IC-low (n = 34); SIRT1-low/N1IC-low (n = 5); SIRT1-high/N1IC-high (n = 81); and SIRT1-low/N1IC-high (n = 30)." (PMID 25420528, 2014). "However, in the same study, ectopic expression of SIRT1 in BRCA1 wild type breast cancer cells did not inhibit tumour formation." (PMID 21698133, 2011). "However, the roles of SIRT1 and FoxOs in breast cancer metastasis have not been elucidated to date." (PMID 36142156, 2022). "In breast cancer cell lines, Kim and colleagues showed that this compound reduces SIRT1 enzymatic activity and protein levels, increases p51 acetylation, reduces nuclear levels of SIRT1 and discloses nonepigenetic effects, specifically, cell growth inhibition and cell cycle arrest at G2/M phase." (PMID 32365701, 2020). "Lower levels of EP300 and higher levels of the nuclear deacetylases, sirtuins (e.g., SIRT1 and SIRT6) were also detected in the BT474-LapR cells, which might also contribute to the reduced FOXO3 activity in BT474-LapR cells and therefore lapatinib resistance in HER2-positive breast cancer cells." (PMID 31357743, 2019). "Thus, ERα and ERβ appear to differentially regulate SIRT1, consistent with a yin-yang action pattern in tissues where both isoforms are co-expressed and with a recent study showing that SIRT3 protein levels are affected by the ERα/ERβ ratio in breast cancer specimens." (PMID 23734259, 2013). "In untreated cells from mammary tumors lacking full-length BRCA1, SIRT1 was significantly lower compared to the BRCA1-wild type, as well as in transgenic mice models." (PMID 40136510, 2025).
breast cancer (continued). "Aged neutrophils induce mitochondrial DNA release by sirtuin 1 (SIRT1), thereby inducing the formation of NETs, rather than the traditional Cit-Histone H3-dependent lytic NET formation, promoting breast cancer lung metastasis." (PMID 37188184, 2023). "In the ERα-negative breast cancer cell line SKBr3, estradiol and GPER agonist G1 increased SIRT1 expression." (PMID 30687231, 2018). "On the one hand, genistein has been demonstrated to enhance SIRT1 expression and activity in C2C12 myotubes and breast cancer T47D cells but not in MCF-7cells." (PMID 28425936, 2017). "These compounds resulted in down-regulation of the DNMT enzymes in the breast cancer cells but not in the MCF-10A cells, thus RES appeared to target SIRT1 specifically in breast cancer but not in normal cells." (PMID 28611316, 2017). "Sirtinol, a SIRT1 inhibitor, induced autophagy with increased LC3-II expression, while caspase activity was not altered in MCF-7 human breast cancer cells." (PMID 26091232, 2015). "The multivariate Cox proportional hazard analyses showed that SIRT1 expression was an independent prognostic factor for RFS, but not for OS in our breast cancer cohort, although a previous publication showed prognostic value for both." (PMID 25139823, 2014). "Interestingly, cytoplasmic FOXO3 was found to be positively correlated with the expression levels of SIRT6 (p < 0.001) but not SIRT1 in HER2+ (ER+ and ER−) breast cancer patients." (PMID 31357743, 2019). "Overexpression of BCAT1 shows that BCAAs catabolism is activated in human breast cancer, and opposing results are observed that the knockdown of BCAT1 can inhibit breast cancer cell growth by activating the mTOR, but not AMPK or SIRT1, signaling mediating mitochondrial biogenesis and function." (PMID 29570613, 2018).
Hyperglycemia (246 papers, 2010 to 2026). An increased concentration of glucose in the blood. "ZLN005 enhances SIRT1 expression and autophagy effectively prevent cardiomyocyte damage caused by excessive hyperglycemia." (PMID 41567643, 2025). "Lipopolysaccharide (LPS)-induced neuroinflammation caused a substantial decrease in SIRT1 in all glycemic backgrounds, as observed earliest in hyperglycemia." (PMID 37511397, 2023). "In this study, we use the Drosophila Genetic Reference Panel to identify genetic variation influencing hyperglycemia associated with loss of Sirt1 function." (PMID 35435227, 2022). "We observed substantial phenotypic variation across the DGRP for hyperglycemia associated with loss of Sirt1." (PMID 35435227, 2022). "Hyperglycemia additionally causes Sirtuin 1 (SIRT1) dysregulation resulting in enhanced histone 3-binding p66Sch promoter acetylation." (PMID 35742837, 2022). "We found that GW501516-activated PPARδ suppresses hyperglycemia-triggered premature senescence of ARPE-19 cells by upregulating SIRT1, which has been implicated in the modulation of lifespan." (PMID 35740104, 2022). "Given the possible association between hyperglycemia and inflammation, the results confirm an inverse relationship between SIRT1 expression and hyperglycemic condition." (PMID 34639171, 2021). "On top of that, it has been implicated that the downregulation of sirtuin-1 (SIRT-1) activity induced by persistent hyperglycemia condition and high insulin environment also plays a significant role in the development of diabetic cardiac inflammation." (PMID 34065781, 2021). "There is evidence that hyperglycemia-induced endothelial dysfunction was associated with sirtuin-1 downregulation and overexpression of vasoactive and profibrotic factors, such as endothelin-1 and TGF-β." (PMID 33519447, 2020). "For instance, hepatic SIRT1 deficiency disrupted mTORC2/Akt signaling to cause hyperglycemia and oxidative stress in mice model." (PMID 33304318, 2020). "Actually, systemic infusion of miR-34a inhibitor or genetic ablation of endothelial miR-34a prevented downregulation of endothelial sirtuin-1 caused by hyperglycemia." (PMID 33519447, 2020). "In summary, these novel findings indicate that BAK exhibits its therapeutic properties against hyperglycemia-caused diabetic cardiomyopathy by attenuating myocardial oxidative damage via activating the SIRT1/Nrf2 signaling." (PMID 33062139, 2020). "We conclude that the SIRT1-PGC-1α-HO-1 axis is pivotal in order to cope with oxidative stress caused by hyperglycemia and has an important role to play in protecting the diabetic heart." (PMID 30071860, 2018). "A previous study showed that hepatic deletion of SIRT1 in mice causes hepatic glucose overproduction, chronic hyperglycemia and oxidative stress." (PMID 29207650, 2017). "The metformin treatment alleviates hyperglycemia-caused senescence and cell death from modulating SIRT1 in the endothelial cells." (PMID 26885898, 2016). "Remarkably, liver-specific SIRT1 deficiency causes hepatic glucose overproduction, chronic hyperglycemia and increased oxidative stress." (PMID 26824477, 2016). "Data from this study demonstrated that hyperglycemia accelerates aging-like process in the vascular ECs and such process is mediated via downregulation of SIRT1, causing reduction of mitochondrial antioxidant enzyme in a p300 and FOXO1 mediated pathway." (PMID 23342163, 2013). "For example, loss of SIRT1 expression leads to hepatic glucose overproduction, hyperglycemia, products of oxidative stress, and inhibition of the gene encoding Rictor that results in impaired TORC2 and Akt signaling." (PMID 23203037, 2012). "Recent work has shown that hepatic SIRT1 deficiency yields hepatic glucose overproduction, hyperglycemia, products of oxidative stress, and inhibition of the gene encoding Rictor that lead to impaired TORC2 and Akt signaling." (PMID 22545721, 2012).